TSLIG3B (tRNA splicing ligase complex subunit 3B)
Description:
Accessory subunit of the tRNA-splicing ligase complex that acts by directly joining spliced tRNA halves to mature-sized tRNAs by incorporating the precursor-derived splice junction phosphate into the mature tRNA as a canonical 3',5'-phosphodiester. May act as an RNA ligase with broad substrate specificity and may function toward other RNAs. Could regulate the expression of PRMT1, a protein arginine N-methyltransferase.
Synonyms: FAM98B; FLJ38426
Tractability: PROTAC: ubiquitination databases record sites on it; its protein half-life has been measured.
Gene: Protein-coding gene on chromosome 15 (38,454,127 to 38,487,710, forward strand). Ensembl gene ENSG00000171262.
Subcellular location: Nucleus; Cytoplasm
Subcellular location (Human Protein Atlas): Nucleoplasm; Vesicles
Pathways (Reactome):
Metabolism of RNA: tRNA processing in the nucleus
Gene Ontology:
Molecular function: identical protein binding; protein binding; protein methyltransferase activity; RNA binding
Biological process: tRNA splicing, via endonucleolytic cleavage and ligation
Cellular component: cytoplasm; nucleoplasm; nucleus; tRNA-splicing ligase complex
Genetic constraint (gnomAD): Loss-of-function variants: 27 observed, 29.04 expected, observed/expected ratio (o/e) 0.93, 90% interval 0.68 to 1.28. The upper end of that interval is the gene's LOEUF score, 1.28, which puts it in group 5 of 6, group 1 being the genes least tolerant of losing a copy. Missense variants: 406 observed, 404.1 expected, observed/expected ratio (o/e) 1, 90% interval 0.93 to 1.09. Synonymous variants: 148 observed, 139.09 expected, observed/expected ratio (o/e) 1.06, 90% interval 0.93 to 1.22.
Homologues: Orthologues: macaque FAM98B (97% identical), pig FAM98B (92% identical), chimpanzee FAM98B (91% identical), dog FAM98B (91% identical), guinea pig FAM98B (90% identical), mouse Fam98b (89% identical), rat Fam98b (88% identical), rat Fam98b-ps1 (87% identical), rabbit FAM98B (66% identical), tropical clawed frog fam98b (54% identical), zebrafish fam98b (39% identical), Drosophila melanogaster CG5913 (37% identical), and 1 more. Paralogues in human: TSLIG3A (57% identical), TSLIG3C (28% identical).
Diseases named in the same sentence as TSLIG3B in open-access papers:
TSLIG3B is named in the same sentence as 8 diseases in open-access papers, as found by Europe PMC text mining. Sharing a sentence is not in itself a finding about the gene and the disease.
TSLIG3B shares sentences with these, for which no sentence is quoted: cancer (4 papers); colorectal cancer (2); liver fibrosis (2); tumor (2); breast carcinoma (1); colon cancer (1); lymphoma (1); Obesity (1).